LRRCC1 (leucine rich repeat and coiled-coil centrosomal protein 1)
Description:
Required for the organization of the mitotic spindle. Maintains the structural integrity of centrosomes during mitosis.
Synonyms: CLERC; KIAA1764; VFL1; CLERK; SAP2
Tractability: PROTAC: ubiquitination databases record sites on it.
Gene: Protein-coding gene on chromosome 8 (85,107,116 to 85,146,080, forward strand). Ensembl gene ENSG00000133739.
Subcellular location: Cytoplasm, cytoskeleton, microtubule organizing center, centrosome, centriole
Subcellular location (Human Protein Atlas): Basal body; Centrosome; Cytosol; Primary cilium; Primary cilium tip; Vesicles
Gene Ontology:
Cellular component: centrosome; centriole
Genetic constraint (gnomAD): Loss-of-function variants: 61 observed, 70.68 expected, observed/expected ratio (o/e) 0.86, 90% interval 0.7 to 1.07. The upper end of that interval is the gene's LOEUF score, 1.07, which puts it in group 4 of 6, group 1 being the genes least tolerant of losing a copy. Missense variants: 740 observed, 754.31 expected, observed/expected ratio (o/e) 0.98, 90% interval 0.92 to 1.04. Synonymous variants: 264 observed, 265.03 expected, observed/expected ratio (o/e) 1, 90% interval 0.9 to 1.1.
Homologues: Orthologues: chimpanzee LRRCC1 (99% identical), macaque LRRCC1 (97% identical), pig LRRCC1 (84% identical), rabbit LRRCC1 (83% identical), mouse Lrrcc1 (80% identical), rat Lrrcc1 (78% identical), tropical clawed frog lrrcc1 (47% identical), zebrafish lrrcc1 (42% identical), Drosophila melanogaster TbCMF46 (7% identical), Drosophila melanogaster Ppr-Y (7% identical). Paralogues in human: LRRC9 (17% identical), CEP97 (10% identical), LRGUK (10% identical), DNAAF1 (9% identical), LRRC49 (9% identical), DRC3 (8% identical), LRRC43 (8% identical), LRRIQ3 (8% identical), DNAAF11 (8% identical), PPP1R42 (6% identical), LRRC46 (5% identical), LRRC61 (5% identical), and 1 more.
Diseases named in the same sentence as LRRCC1 in open-access papers:
LRRCC1 is named in the same sentence as 3 diseases in open-access papers, as found by Europe PMC text mining. Sharing a sentence is not in itself a finding about the gene and the disease. The quoted sentences say what the papers report.
ciliopathy (2 papers, 2016 to 2022). A genetic disorder of the cellular cilia or the cilia anchoring structures, the basal bodies, or of ciliary function. "Since a mutation in the LRRCC1 gene has been identified in Joubert syndrome patients, this finding is relevant in the context of human ciliopathies." (PMID 35319462, 2022). "Furthermore, a homozygous mutation in the LRRCC1 gene was identified in two siblings affected by a ciliopathy called Joubert syndrome (JBTS), suggesting that LRRCC1 might somehow affect the function of non-motile cilia." (PMID 35319462, 2022). "In either case, our observations in RPE1 cells are consistent with the JBTS diagnosis in two siblings carrying a mutation in the LRRCC1 gene, further establishing that LRRCC1 is a novel ciliopathy gene." (PMID 35319462, 2022). "LRRCC1 affects the recruitment at centrioles of another ciliopathy protein called C2CD3 (C2 domain containing 3), which we found to also localize in a rotationally asymmetric manner, forming a pattern partly reminiscent of the acorn described in flagellates." (PMID 35319462, 2022). "Of the remaining 40 families, nine (22.5%) had variants in eight novel candidate ciliopathy genes (TXNDC15, TRAPPC3, EXOC3L2, FAM98C, C17orf61, LRRCC1, NEK4, and CELSR2)." (PMID 27894351, 2016).
Joubert syndrome (2 papers, 2016 to 2022). Joubert syndrome (JS) is characterized by congenital malformation of the brainstem and agenesis or hypoplasia of the cerebellar vermis leading to an abnormal respiratory pattern, nystagmus, hypotonia, ataxia, and delay in achieving motor milestones. "Finally, LRRCC1, a novel candidate we identified in a family with Joubert syndrome, is also known as CLERC (centrosomal leucine-rich repeat and coiled-coil containing protein) because of its established role as a centrosomal protein in mitosis spindle organization." (PMID 27894351, 2016).
LRRCC1 also shares sentences with these, for which no sentence is quoted: cancer (1 paper).